OPTC (opticin)
Description:
Inhibits angiogenesis in the vitreous humor of the eye, and therefore represses neovascularization (By similarity). Binds collagen fibrils (By similarity). May be involved in collagen fiber organization via regulation of other members of the small leucine-rich repeat proteoglycan superfamily (By similarity).
Synonyms: OPT
Tractability: Antibody: UniProt places it where antibodies can reach, with high confidence; its Gene Ontology location is reachable by antibodies, with high confidence; UniProt predicts a signal peptide or a membrane-spanning region.
Gene: Protein-coding gene on chromosome 1 (203,494,121 to 203,508,949, forward strand). Ensembl gene ENSG00000188770.
Subcellular location: Secreted, extracellular space, extracellular matrix
Pathways (Reactome):
Extracellular matrix organization: Degradation of the extracellular matrix
Gene Ontology:
Molecular function: extracellular matrix structural constituent
Biological process: articular cartilage development; bone development; collagen fibril organization
Cellular component: extracellular matrix; extracellular region; gel phase of interstitial matrix
Genetic constraint (gnomAD): Loss-of-function variants: 21 observed, 24.54 expected, observed/expected ratio (o/e) 0.86, 90% interval 0.61 to 1.23. The upper end of that interval is the gene's LOEUF score, 1.23, which puts it in group 5 of 6, group 1 being the genes least tolerant of losing a copy. Missense variants: 416 observed, 445.38 expected, observed/expected ratio (o/e) 0.93, 90% interval 0.86 to 1.01. Synonymous variants: 167 observed, 187.57 expected, observed/expected ratio (o/e) 0.89, 90% interval 0.78 to 1.01.
Homologues: Orthologues: chimpanzee OPTC (99% identical), macaque OPTC (95% identical), dog OPTC (75% identical), pig OPTC (75% identical), mouse Optc (72% identical), rat Optc (71% identical), rabbit OPTC (65% identical), guinea pig OPTC (63% identical), tropical clawed frog optc (39% identical), Caenorhabditis elegans lron-7 (28% identical). Paralogues in human: LRWD1 (20% identical).
Diseases named in the same sentence as OPTC in open-access papers:
OPTC is named in the same sentence as 20 diseases in open-access papers, as found by Europe PMC text mining. Sharing a sentence is not in itself a finding about the gene and the disease. The quoted sentences say what the papers report.
glaucoma (5 papers, 2007 to 2024). Increased pressure in the eyeball due to obstruction of the outflow of aqueous humor. "Other genetic factors, e.g., optic atrophy 1 (OPA1), apolipoprotein E, E-cadherin, neurotrophin-4 (NTF-4) and opticin (OPTC), have been reported to elevate the risk of retinal degeneration, a characteristic of glaucoma." (PMID 22509108, 2012). "Given its expression in the optic nerve, it is likely a mutation in the OPTC gene is also involved in initiating glaucoma." (PMID 17563717, 2007). "It is worthwhile to mention here that it remains important to show functional correlation of the suspected opticin variants with glaucoma pathogenesis to further substantiate role of the gene in the disease process." (PMID 17359525, 2007). "Those rare variants are located in CYP1B1, SIX6, CARD10, MFN1, OPTC, OPTN, and WDR36 glaucoma-related genes." (PMID 38241218, 2024). "OPTC is widely expressed in ocular tissue and was screened as a candidate gene in patients with high myopia, glaucoma, and age-related macular degeneration." (PMID 19844586, 2009). "We investigated the molecular basis of primary open-angle glaucoma (POAG) using Opticin (OPTC) as a candidate gene on the basis of its expression in the trabecular meshwork cells involved in the disease pathogenesis." (PMID 17359525, 2007). "To rule out the OPTC gene as a glaucoma gene, we screened this gene in our POAG data set." (PMID 17563717, 2007).
age-related macular degeneration (2 papers, 2007 to 2009). Age-related loss of vision in the central portion of the retina (macula), secondary to retinal degeneration. "The OPTC (opticin) gene encodes a protein that is a member of the small leucine-rich repeat protein (SLRP) family, and is located on chromosome 1q31-q32 within an age-related macular degeneration (AMD) susceptibility locus." (PMID 17563717, 2007).
myopia (2 papers, 2009 to 2021). "The purpose of this study was to test whether mutations in the two members of the class III SLRPs, opticin (OPTC) and dermatan sulfate proteoglycan 3 (EPYC), are responsible for high myopia." (PMID 19844586, 2009). "More interestingly, we found that two of them, apolipoprotein A1 (APOA1) and opticin (OPTC), commonly had high expression in either myopia or control patients." (PMID 33850473, 2021). "In summary, our results suggest that both OPTC and EPYC are unlikely to play a major role in high myopia." (PMID 19844586, 2009).
osteoarthritis (2 papers, 2018 to 2020). A noninflammatory degenerative joint disease occurring chiefly in older persons, characterized by degeneration of the articular cartilage, hypertrophy of bone at the margins and changes in the synovial membrane. "Opticin null mice showed protection against osteoarthritis and it was found that these mice had increased levels of lumican and epiphycan, and decreased levels of fibromodulin." (PMID 32764753, 2020). "It has also been demonstrated that opticin deficient mice are protected against osteoarthritis because the lack of opticin results in an alteration in the amounts of other SLRPs in cartilage leading to altered fibril diameter and increased protection from proteolysis." (PMID 32764753, 2020).
retinopathy of prematurity (2 papers, 2021 to 2022). A bilateral retinopathy characterized by neovascularization, scarring, retinal detachment, and eventually blindness. "Our findings support the hypothesis that intraocular administration of recombinant human opticin offers the potential for a safe and effective therapy for neovascular diseases of the retina including retinopathy of prematurity." (PMID 34954204, 2022).
glioma (1 paper, 2023). A benign or malignant brain and spinal cord tumor that arises from glial cells (astrocytes, oligodendrocytes, ependymal cells). "For the sake of clarifying the expression of BMGs in glioma, this study screened 9 BMGs that were upregulated in glioma (FBN2, FREM3, Lamb4, MEP1A, MMP1, MMP7, OPTC, EVA1A, and ADAMTS20) from TCGA -GTEX expression matrix." (PMID 37335645, 2023).
lymphoma (1 paper, 2013). A malignant (clonal) proliferation of B- lymphocytes or T- lymphocytes which involves the lymph nodes, bone marrow and/or extranodal sites. "In this study, OPTC was expressed in the leukemic cells of all CLL patients and in the lymphoma cells of some patients with MCL." (PMID 24499526, 2013).
lymphoplasmacytoid lymphoma (1 paper, 2013). "OPTC was also expressed in tumor cells of some MCL patients (2/8) but not in tumor cells from other hematological malignancies e.g. AML, CML, PLL, HCL, FL, lymphoplasmacytoid lymphoma, MM, and ALL." (PMID 24499526, 2013).
mantle cell lymphoma (1 paper, 2013). Mantle cell lymphoma is a rare form of malignant non-Hodgkin lymphoma affecting B lymphocytes in the lymph nodes in a region called the ``mantle zone''. "OPTC was expressed at the gene level in all patients with CLL (n = 90) and in 2/8 patients with mantle cell lymphoma (MCL) but not in blood mononuclear cells of healthy control donors (n = 20) or in tumor samples from nine other types of hematological malignancies." (PMID 24499526, 2013).
normal tension glaucoma (1 paper, 2012). "We observed expression of seven genes which were previously genetically associated with POAG (included normal tension glaucoma (NTG)), namely APOE, CAV1, EDNRA, MYOC, OPTC and TMCO1." (PMID 23028713, 2012).
vitreous hemorrhage (1 paper, 2019). Blood extravasation in the vitreous humor. "Angiogenesis and vitreous hemorrhage are key features of CAPN5-NIV disease and downregulation of opticin may contribute to the increased retinal neovascularization seen in these patients." (PMID 31110225, 2019).
retinopathy (2 papers, 2014 to 2022). "In this study, therefore, the zebrafish model of hypoxia-induced retinopathy was established in vivo to further investigate the specific regulatory role of opticin at the integrin-collagen binding site and its underlying mechanism." (PMID 35006271, 2022). "To further study the regulation role of opticin on collagen-induced neovascularization in vivo and its potential mechanism, we generated a hypoxia-induced retinopathy zebrafish model." (PMID 35006271, 2022). "In vivo comparisons of wild-type and opticin knockout animals in the oxygen-induced retinopathy model of neovascularization showed more neovascularization in the knockout animal." (PMID 25136834, 2014). "Opticin and OPTC-overexpressing plasmid injection reduced retinal neovascularization in the zebrafish model of hypoxia-induced retinopathy." (PMID 35006271, 2022).
hematological malignancies (1 paper, 2013). "The expression of OPTC was tested by RT-PCR and realtime qPCR in PBMC from CLL patients, other hematological malignancies and healthy controls." (PMID 24499526, 2013).
OPTC also shares sentences with these, for which no sentence is quoted: primary open angle glaucoma (2 papers); cancer (1); chronic lymphocytic leukemia (1); melanoma (1); retinal degeneration (1); retinal vascular disorder (1); tumor (1).